GAPDH (glyceraldehyde-3-phosphate dehydrogenase)
Description:
Catalyzes the conversion of D-glyceraldehyde 3-phosphate (G3P) into 3-phospho-D-glyceroyl phosphate in glycolysis and the reverse reaction in gluconeogenesis. Also shows nitrosylase activity, thereby playing a role in nuclear functions. Modulates the organization and assembly of the cytoskeleton (By similarity). Facilitates the CHP1-dependent microtubule and membrane associations through its ability to stimulate the binding of CHP1 to microtubules (By similarity). Component of the GAIT (gamma interferon-activated inhibitor of translation) complex which mediates interferon-gamma-induced transcript-selective translation inhibition in inflammation processes. Upon interferon-gamma treatment assembles into the GAIT complex which binds to stem loop-containing GAIT elements in the 3'-UTR of diverse inflammatory mRNAs (such as ceruplasmin) and suppresses their translation. Also plays a role in innate immunity by promoting TNF-induced NF-kappa-B activation and type I interferon production, via interaction with TRAF2 and TRAF3, respectively. Participates in nuclear events including transcription, RNA transport, DNA replication and apoptosis (By similarity). Nuclear functions are probably due to the nitrosylase activity that mediates cysteine S-nitrosylation of nuclear target proteins such as SIRT1, HDAC2 and PRKDC (By similarity).
Synonyms: GAPD; G3PD; HEL-S-162eP
Tractability: Small molecule: a structure with a bound ligand is known; a high-quality ligand is known; it has a high-quality binding pocket; it belongs to a druggable protein family. Antibody: its Gene Ontology location is reachable by antibodies, with high confidence; the Human Protein Atlas places it where antibodies can reach. PROTAC: UniProt records ubiquitination sites on it; ubiquitination databases record sites on it; its protein half-life has been measured; a small molecule that binds it is known.
Target class: Enzyme; Oxidoreductase
Gene: Protein-coding gene on chromosome 12 (6,534,012 to 6,538,930, forward strand). Ensembl gene ENSG00000111640.
Subcellular location: Cytoplasm, cytosol; Nucleus; Cytoplasm, perinuclear region; Membrane; Cytoplasm, cytoskeleton
Subcellular location (Human Protein Atlas): Cytosol; Plasma membrane; Nuclear membrane; Vesicles
Pathways (Reactome):
Metabolism: Gluconeogenesis; Glycolysis
Gene Ontology:
Molecular function: aspartic-type endopeptidase inhibitor activity; disordered domain specific binding; glyceraldehyde-3-phosphate dehydrogenase (NAD+) (phosphorylating) activity; identical protein binding; protein binding; microtubule binding; peptidyl-cysteine S-nitrosylase activity; NAD binding; NADP binding; oxidoreductase activity, acting on the aldehyde or oxo group of donors, NAD or NADP as acceptor
Biological process: antifungal innate immune response; antimicrobial humoral immune response mediated by antimicrobial peptide; canonical glycolysis; cellular response to type II interferon; negative regulation of translation; positive regulation of canonical NF-kappaB signal transduction; positive regulation of type I interferon production; gluconeogenesis; microtubule cytoskeleton organization; negative regulation of formation of translation preinitiation complex; neuron apoptotic process; peptidyl-cysteine S-trans-nitrosylation; protein stabilization; regulation of macroautophagy; glucose metabolic process; glycolytic process
Cellular component: cytoplasm; cytosol; extracellular exosome; GAIT complex; lipid droplet; membrane; nucleus; plasma membrane; ribonucleoprotein complex; vesicle; microtubule cytoskeleton; cytoskeleton; perinuclear region of cytoplasm
Genetic constraint (gnomAD): Loss-of-function variants: 13 observed, 30.45 expected, observed/expected ratio (o/e) 0.43, 90% interval 0.28 to 0.68. The synonymous counts are far from expectation, so gnomAD's model fits this gene poorly and the ratio says little. Missense variants: 300 observed, 444.8 expected, observed/expected ratio (o/e) 0.67, 90% interval 0.61 to 0.74. Synonymous variants: 211 observed, 165.83 expected, observed/expected ratio (o/e) 1.27, 90% interval 1.14 to 1.43.
Homologues: Orthologues: chimpanzee GAPDH (100% identical), macaque GAPDH (99% identical), pig GAPDH (95% identical), dog GAPDH (95% identical), rabbit GAPDH (94% identical), guinea pig GAPDH (94% identical), mouse Gapdh (93% identical), rat Gapdh (93% identical), mouse Gapdhrt2 (93% identical), mouse Gapdhrt (93% identical), rat Gapdhl10 (93% identical), zebrafish gapdh (86% identical), and 9 more. Paralogues in human: GAPDHS (68% identical).
Diseases named in the same sentence as GAPDH in open-access papers:
GAPDH is named in the same sentence as 411 diseases in open-access papers, as found by Europe PMC text mining. Sharing a sentence is not in itself a finding about the gene and the disease. The quoted sentences say what the papers report.
breast carcinoma (122 papers, 1994 to 2026). "We first found that acrolein-conjugated glyceraldehyde-3-phosphate dehydrogenase (GAPDH) translocated to the nucleus and caused apoptosis in mouse mammary carcinoma FM3A cells." (PMID 37511605, 2023). "Previous studies have shown that single nucleotide polymorphisms (SNPs) in the hsa-miR-548 family binding site at the glyceraldehyde-3-phosphate dehydrogenase alter susceptibility to breast cancer." (PMID 34395634, 2021). "For example, the association of GAPDH expression with the aggressiveness of breast cancer and its upregulation in oestradiol treated MCF7 cells or its downregulation in amino-bisphosphonate treated MCF7 and T47D cell lines." (PMID 34752497, 2021). "Amplification of 12p13 region was observed in breast cancer, T cell lymphomas and lymphocytic leukemia, causing over-expression of GAPDH, mir-141 and -200c." (PMID 24796549, 2014). "GAPDH has been identified in EVs associated with breast cancer." (PMID 40214422, 2025). "Moreover, GAPDH over-expression accelerated the aging process in breast cancer cells due to telomerase inhibition caused by an interaction between the GAPDH and the telomerase RNA." (PMID 32370188, 2020). "In addition, future studies are needed to determine the relevance of GAPDH in the proliferation, migration, invasion, and metastasis of breast cancer cells since GAPDH expression is found to be associated with breast cancer cell proliferation and tumor aggression in patients with breast cancer." (PMID 40214422, 2025). "Breast cancer gene expression was measured at each time point, and relative expression levels were normalized to GAPDH." (PMID 40558895, 2025). "At the same time, GAPDH is also identified as a key factor with respect to proliferation and aggressiveness of breast cancer cells, which has a significant positive correlation with higher histoprognostic grades." (PMID 39954675, 2025). "The obtained Ct values were directly proportional to the concentration of these breast cancer hormonal receptors which averages were used to calculate the degree of over expression using GAPDH as a housekeeping gene." (PMID 39752420, 2025). "Although there is a paucity of information regarding the relevance of GAPDH to breast cancer cell survival, studies have established that the enzyme is largely involved in the adaptation of breast cancer to hypoxia." (PMID 40214422, 2025). "The total score of all algorithms combined was lowest for ACTB, followed by RPL13a and GAPDH, making these genes the most stable ones in the combined data set in the breast cancer cell lines studied." (PMID 40133575, 2025). "In this study, we investigated the effects of DC-5163, a novel small-molecule inhibitor that targets GAPDH, on breast cancer in detail." (PMID 38811918, 2024). "Taken together, our results demonstrated that DC-5163, a novel inhibitor targeting GAPDH, suppressed aerobic glycolysis and reduced the energy supply of breast cancer cells, thereby leading to the inhibition of proliferation and increase of apoptosis." (PMID 38811918, 2024). "For example, DC-5163, a GAPDH inhibitor, effectively treats breast cancer by reducing energy supply through the inhibition of glycolysis." (PMID 39199428, 2024). "DC-5163 inhibited GAPDH activity in five different cancer cell lines including human breast cancer cells, human colon cancer cells, and human lung cancer cells." (PMID 38811918, 2024). "Studies have pointed out that the expression of GAPDH in lung cancer, kidney cancer, breast cancer, and other tumors is out of control." (PMID 35190747, 2022). "Our studies found that the NDV AMHA1 strain inhibits the glycolysis pathway in breast cancer cells by interfering with glycolysis enzymes such as hexokinase and GAPDH." (PMID 36172043, 2022). "There is also research evidence showing that the GAPDH expression level and tumor metastasis in patients with breast cancer is correlated." (PMID 35268705, 2022).
breast carcinoma (continued). "The assessment of the protein levels of ANXA2 and EpCAM relative to GAPDH showed that ANXA2 is expressed in all breast cancer cell lines whilst EpCAM is expressed only in the ERα+ cells ZR‐75‐1 and MCF‐7." (PMID 34240826, 2022). "As a multifunctional gene, the use of GAPDH as a reference gene has been also questioned and challenged in other cancers including lung cancer, breast cancer and bladder cancer." (PMID 33630851, 2021). "Nevertheless, existing evidence indicates that the expression of GAPDH in breast cancer tissues or cell lines would be changed under different pathological conditions or experimental treatments." (PMID 34752497, 2021). "According to the ΔCt method, TRA2B, RHOA, and THRAP3 were the most stably expressed genes, while DNAJC8, GAPDH, and B2M were the least stable genes in the breast cancer tissue group, which was consistent with the analysis according to NormFinder." (PMID 34895237, 2021). "Of these proteins, previous studies have shown that high expression of glyceraldehyde-3-phosphate dehydrogenase, peroxiredoxin-2 and histone H2A type 2-A in breast cancer tissues are inversely correlated with overall survival and tumour aggressiveness." (PMID 34832109, 2021). "After extracting DNA from 59 FFPE breast cancer samples, and 11 benign breast lesions as control, we used PCR for the GAPDH gene to check the quality of DNA samples." (PMID 33482849, 2021). "Various other reference genes in the past have been described to be suitable reference genes in breast cancers including GAPDH, ACTB, PPIA and RNA28S/RNA18S." (PMID 34681026, 2021). "In breast cancer cell lines, GAPDH, TBP, and UBC were the most stable reference genes almost equally." (PMID 34752497, 2021). "When irradiated with the same dose as the E. coli cells used herein, the human breast carcinoma cell line MDA-MB-231 exhibits the same IR-induced sulfonic acid modification on the catalytic Cys of GAPDH." (PMID 32536603, 2020). "Here we show in a group of breast cancer patients an apparent shortening of the transverse relaxation time of the Pi signal, as compared with fibroglandular breast tissue of healthy volunteers, which could well be caused by a mobility restriction on Pi by enzymatic interaction with GAPDH." (PMID 30311703, 2019). "The expression of LINC01133 was examined in 74 human breast cancer tissues and adjacent normal tissues using qRT‐PCR with normalization to GAPDH." (PMID 31557401, 2019). "We observed the downregulation of the GAPDH gene as early as 12 h after treatment in mouse mammary adenocarcinoma AMN3 cells while it was earlier at 6 h after exposure in human breast cancer AMJ13 cells." (PMID 31612140, 2019). "To precisely quantify colonization of mouse lungs by the breast cancer cells, we used a protocol were the ratio of Human/Mouse cells is determined by q-PCR using primers for human and mouse GAPDH, respectively (Human GAPDH /Mouse GAPDH)." (PMID 31828042, 2019). "Our results suggest the effectiveness of a novel strategy for anti-breast cancer therapy through glycolysis inhibition and GAPDH downregulation." (PMID 31612140, 2019). "The extracted DNA from FFPE breast cancer tissue was successfully amplified using GAPDH primers indicating good quality DNA for further viral detection assay." (PMID 29299053, 2017). "The GAPDH gene has been classically used as a housekeeping gene, but in more recent years it has been shown to be over-expressed in many tumors including breast cancer and to be correlated with a poor prognosis and an increased drug resistance." (PMID 28686225, 2017). "In an investigation of canine articular connective tissue, GAPDH and B2M were found to be highly stable, while in canine mammary tumors, GAPDH was less stable." (PMID 29178874, 2017). "Functional delivery was assessed in both HER2-overexpressing ovarian and breast cancer cells using siRNA directed against the ubiquitously expressed glyceraldehyde-3-phosphate dehydrogenase (GAPD) enzyme gene." (PMID 26840082, 2016).
breast carcinoma (continued). "Even so, GAPDH continues to be utilized as a normalizer in breast cancer and cell line studies with RT-qPCR." (PMID 25617865, 2015). "The fact that we examined quality DNA from tumor specimens of breast carcinoma by Multiplex PCR for GAPDH in all samples amplified a set of different-sized targets." (PMID 23557440, 2013). "The inhibition of LLL12 on these STAT3 target genes in ALDH+ stem cell-like breast cancer cells was quantified and normalized to GAPDH." (PMID 24376586, 2013). "Based on the GAPDH positively associated gene expression levels, the subclass of NSCLC, adrenocortical carcinoma, breast cancer and HCC can also be classified to various stages." (PMID 23620736, 2013). "Primers and reaction conditions used for amplification of adenylyl cyclases, opioid receptors and GAPDH in human breast cancer cells." (PMID 23308242, 2013). "In agreement with our results, Révillion and co-workers reported reduced OS and relapse-free survival among breast cancer patients with enhanced GAPDH mRNA expression as assessed by real-time PCR." (PMID 24252137, 2013). "The expression of TopBP1 gene at the mRNA level in normal breast tissue and hereditary breast cancer was estimated by real-time quantitative PCR analysis with GAPDH gene applied as a reference." (PMID 22544570, 2012). "In another study, GAPDH was suggested as the target gene in the evaluation of amino-bisphosphophates effects on prostate and breast cancer cell lines." (PMID 20707929, 2010). "The average Ct values of GAPDH ranged from 20.16 to 24.71 in blood samples of patients with breast cancer and from 21.73 to 25.73 in whole blood samples of the control group, respectively." (PMID 20025731, 2009). "Standardized mRNA levels of AQP5 (AQP5 mRNA/GAPDH mRNA) in lung and breast cancer tissue (positive control) and normal peripheral blood lymphocytes (negative control) were compared to that of CML cells for comparison." (PMID 18612408, 2008). "Two of the most commonly used endogenous control genes for breast cancer gene expression studies are glyceraldehyde-3-phosphate dehydrogenase (GAPDH) and β-actin (ACTB) but their reliability in this context has not been demonstrated." (PMID 18042273, 2007). "In breast cancer cells treated with endoxifen GAPDH was used to normalize the expression data of the progesterone receptor mRNA." (PMID 16515701, 2006). "In the present study, we have quantified by real time RT PCR the effect of the BPs on the expression of the GAPDH gene in prostate cancer cells (PC-3; DU-145) and in breast cancer cells (MCF-7; T-47D)." (PMID 16515701, 2006). "Consistent with its expression in the EVs, GAPDH is also overexpressed in breast cancer." (PMID 40214422, 2025). "Furthermore, PFK1 and GAPDH show even higher protein expression levels in malignant breast cancer tissues from obese women." (PMID 41007296, 2025). "Our findings not only provide novel insights into DC-5163 as a promising GAPDH inhibitor for suppressing breast cancer but also indicate that PET/CT may be used as an effective noninvasive method for monitoring the efficacy of DC-5163 treatment." (PMID 38811918, 2024). "Theelectrochemical genosensing approach allows the quantitative measurementof transcripts with high sensitivity, robustness, and simplicity.To the best of the authors’ knowledge, this is the first studyon the expression of GAPDH genes in exosomes from breast cancer patients." (PMID 36683335, 2023).